EGFR (epidermal growth factor receptor)
Diseases named in the same sentence as EGFR in open-access papers (continued):
Sharing a sentence is not in itself a finding about the gene and the disease.
oral cancer (continued). "We also investigated the effect of capsaicin on the expression of oral cancer cell proliferation factors SOCS3, EGFR (epidermal growth factor receptor), STAT3 and PI3K (phosphoinositide 3-kinase) in the presence or absence of bacterial antigens." (PMID 34445392, 2021). "Combined treatment of curcumin and cetuximab markedly suppressed protein expression of EGFR and ERK phosphorylation in oral cancer cells." (PMID 33946151, 2021). "Previous studies have found evidence of EGFR overexpression in human head and neck SCC, and oral cancers have been reported to demonstrate evidence of mRNA expression for EGFR." (PMID 34575510, 2021). "Combination of erlotinib targeting EGFR along with VEGF inhibitors has also shown desirable results in clinical phase I and II trials in metastatic and recurrent oral cancer." (PMID 35047986, 2020). "Cetuximab, a mouse-human chimeric antibody (IgG1) that targets epidermal growth factor receptor (EGFR), was recently approved for treatment of oral cancer." (PMID 32765652, 2020). "Recently, cetuximab, a mouse-human chimeric mAb (IgG1) that targets epidermal growth factor receptor (EGFR), was approved by the Food and Drug Administration (FDA) in the USA for treatment of oral cancers." (PMID 33000243, 2020). "Quercetin treatment suppressed cell growth by inducing G2/M arrest and apoptosis in EGFR-overexpressing HSC-3 and TW206 oral cancer cells." (PMID 32050534, 2020). "The elevated expression of epidermal growth factor (EGF), EGFR, Janus kinase (JAK) and proto-oncogene tyrosine-protein kinase Src (Src) is noted in human oral cancer." (PMID 30001383, 2018). "Both HuR and EGFR are often dysregulated in OPSCC and EGFR is a commonly targeted pathway in human oral cancer." (PMID 30289952, 2018). "Encouraged by the observation that NAC suppressed EGFR-induced phosphorylation in an earlier study, the effects of NAC in EGFR-overexpressing invasive oral cancer was conducted on cancer cell growth in a murine xenograft model." (PMID 29849877, 2018). "Differentially expressed microRNAs have been found to tightly regulate four of the possible biomarkers that we identified—HMGA2, EGFR, HOXA1, and ABCC5/ABCC4 —further supporting their involvement in oral-cancer progression." (PMID 26179909, 2015). "According to the facts that CAPE treatment is able to inhibit the activity and abundance of EGFR and COX-2, we believe that administration of CAPE can prevent and delay the development or progression of oral cancers." (PMID 25984601, 2015). "Among the 4 hub genes, the three genes EGFR, PDGFRB, STAT5A have already been annotated to be related to oral cancer according to GeneCards." (PMID 26064958, 2015). "Therefore, EGF may be a better target for the therapy of oral cancer than EGFR." (PMID 24765152, 2014). "EGFR, in turn, activates downstream signaling cascades, including STAT, JNK and PI3K/AKT, known to promote tumorigenesis in oral cancer." (PMID 24742667, 2014). "The results demonstrate LPA-stimulated migration in oral carcinoma cells through LPAR3, mediated further by PKC, which acts either in concert with or independently of EGFR transactivation." (PMID 24928086, 2014). "Besides decorin-EGFR relation, additional interactions with other nuclear and/or cytosolic factors may result from the aberrant localization of decorin and perhaps result in some of decorin's tumor-promoting role in oral cancer." (PMID 21958730, 2011).
oral cancer (continued). "In this study, we demonstrated that in oral cancer, a typical hypoxic tumor, hypoxia can induce chronic but constitutive phosphorylation of wild-type EGFR in the absence of ligands." (PMID 40940319, 2025). "Mcl-1 is known to be regulated by EGFR signaling pathway in cancer, but there is a lack of research into the clinical correlation between EGFR and Mcl-1 in cancer, particularly, oral cancer." (PMID 38888847, 2025). "Intense proliferative processes involve the overexpression of growth factor receptors, such as epidermal growth factor receptor (EGFR) and human epidermal growth factor receptor 2 (HER2), and the proliferation marker Ki-67, which are hallmarks of oral cancer development." (PMID 40227635, 2025). "We demonstrate that afatinib, a second-generation EGFR-TKI, exhibits stronger anticancer effects compared to gefitinib in oral cancer cell lines lacking the EGFR790M mutation." (PMID 38888847, 2025). "More importantly, our study also showed that blockade of EUDAL/EGFR/STAT3/autophagy signaling can sensitize tumor cells to chemotherapy and that the EUDAL/EGFR/STAT3/autophagy signaling status can predict the drug response in patients with oral cancer." (PMID 40940319, 2025). "A recent study also reported that αvβ6, EGFR, CD17, McM2, Geminin and Ki-67 could differentiate oral cancer and HGD with 78% sensitivity." (PMID 37747904, 2023). "Most data presented here support that repurposing EGFR inhibitors as non-opioid analgesics in oral cancer pain is promising and warrants further research." (PMID 38004424, 2023). "Despite the relevance of EGFR, it seems surprising that there are no published evidence-based results through systematic reviews and meta-analyses specifically designed for oral cancer to date." (PMID 37569265, 2023). "TGFα and EGFR also been reported to play important role in the proliferation of oral cancer cells but not in the proliferation of normal epithelium." (PMID 35681586, 2022). "The expression of EGFR and COX-2 is known to upregulate in oral cancer." (PMID 35774603, 2022). "In another study, it is reported that there are about 14 essential genes involved in oral cancer genesis from leukoplakia, including Signal Transducer and Activator of Transcription 5B (STAT5B) and Epidermal Growth Factor Receptor (EGFR), and eight miRs, such as miR-549, miR-205, and miR-21." (PMID 34946938, 2021). "Furthermore, in hyperglycemic-pancreatic and oral cancer cells, curcumin was found to reduce cell proliferation by inhibiting the EGF/EGFR/Akt pathway." (PMID 34867402, 2021). "An increased expression of EGFR can be found in almost 90% of oral cancers and it is a negative prognostic indicator." (PMID 35002542, 2021). "The efficacy of apatinib combined with anti-EGFR targeted and systemic chemotherapy for the treatment of oral cancer has not been previously reported." (PMID 34761117, 2021). "Targeting multiple targets, such as EGFR, HER2, PODXL, and CD44 may be needed for effective therapy to conquer oral cancers." (PMID 33000243, 2020). "As c-Met and EGFR have the same downstream pathways, the activation of MET-HGFR cascade may identify a therapeutic target in oral cancer especially in patients with resistance to EGFR-targeted therapies." (PMID 35047986, 2020). "Targeting multiple targets, such as PODXL, EGFR, HER2, and PD-L1 may be needed for effective therapy to cure oral cancers." (PMID 32923698, 2020). "Here, we addressed the role of signaling pathways involved in HPV16 E7-mediated PIR/NF-κB activation and oral cell migration, finding that HPV16 E7 promotes the activation of the EGFR/PI3K/AKT/NRF2 signaling pathway, in turn stimulating PIR-mediated NF-κB activation in oral cancer cells." (PMID 32679705, 2020). "In the oral cancer cells (HSC4, OSC19) that were used in this study, high expression of EGFR was confirmed, but no mutations of BRAF, HRAS, KRAS, and NRAS were observed." (PMID 32878053, 2020).
oral cancer (continued). "Alterations in the EGFR gene copy number, or alterations in miR-7, miR-21, mRNA-KIFGA, OPN, DEPDC1B, EZH2, deltaNp63, and DNMT3B were significant for early evaluation and correlation with oral cancer." (PMID 31019584, 2019). "A blocking peptide (375–394 amino acids of EGFR) neutralized the EMab-134 reaction against oral cancer cells in flow cytometry and immunohistochemistry." (PMID 29872734, 2018). "Furthermore, the downstreams of EGFR pathway such as MAPK, JNK, ERK1/2, and so on exerting a regulation of proliferation in numerous tumors including oral cancer have been well documented." (PMID 29752448, 2018). "This genetic signature marker contains LRP12, CCND1, EGFR and TPM2 genes that could predict clinical outcomes and facilitate selection of therapeutic strategies in oral cancer management that are tailor-made for patients." (PMID 28384287, 2017). "Interestingly, EGFR and CCND1 oncogenic events are known to act via a common RAS-MAPK Kinase pathway to promote cell cycle and known to act as a driver of oral cancer tumorigenesis." (PMID 28939077, 2017). "EGFR is a membrane bound tyrosine kinase receptor, which phosphorylates MEK/Erk, STAT3, and mTOR signal molecules for regulation of cell survival and mitosis in many types of malignancy, including oral cancer." (PMID 29212184, 2017). "To determine whether cetuximab, which is a competitive inhibitor of the EGFR pathway and approved for HNC in the clinical setting, has a cytotoxic effect on oral cancer cells, we first performed a proliferation assay." (PMID 26655729, 2015). "CYP4501A1, reactive oxygen species (ROS), EGFR, Src and Ras signaling pathways could all play a role in ANE-induced pathogenesis of oral cancer." (PMID 25051199, 2014). "Recently, EGFR expression, activation and downstream k-Ras as well as mitogen-activated protein kinase (MAPK) signaling are shown to be involved in the pathogenesis oral cancer." (PMID 25051199, 2014). "Since upregulation of DPAGT1 expression in OSCC is associated with increased modification of glycoproteins with complex N-glycans, it is likely that in the absence of mutations these structures are responsible for the observed increased activities of EGFR and FGFR in oral cancer." (PMID 24742667, 2014). "EGFR or HER2 might not affect oral cancer angiogenesis because their common inhibitor, lapatinib, does not inhibit angiogenesis in HNSCC cells." (PMID 40227635, 2025). "Nevertheless, similar strategies used in treating cancer can be adopted for pain, such as developing new generations of EGFR inhibitors, employing different combinations of EGFR inhibitors, and/or combinations with non-EGFR inhibitors to develop non-opioid analgesics to treat oral cancer pain." (PMID 38004424, 2023). "However, as shown in A431 cells, oral cancer cells express both full-length EGFR and EGFR lacking the intracellular domain." (PMID 33449240, 2021). "Therefore, BRB treatment did not alter the strong EGFR expression seen in invasive oral cancers induced by DBPDE exposure." (PMID 34784403, 2021). "It is not yet known whether EGFR plays a role in the aberrant expression of β-catenin that is seen in oral cancer." (PMID 20302655, 2010). "However, similar interactions between EGFR and miR-140 have not been explored in oral cancers." (PMID 37316916, 2023). "The lncRNA ELDR (EGFR long noncoding downstream RNA) was recently shown to be highly expressed in oral cancers as compared to adjacent nontumor tissue, and we previously reported that ELDR may be an oncogene as inhibition of ELDR reduces tumor growth in oral cancer models." (PMID 35378133, 2022).
oral cancer (continued). "To rule out the possible influence of chemotherapy on the activation of EUDAL/EGFR/STAT3/autophagy axis, we collected tumor samples from an additional 45 oral cancer patients who did not receive chemotherapy." (PMID 40940319, 2025). "Therefore, we presumed that EGFR should be an activin A target gene through SP1 activation; however, the regulation of activin A and EGFR has never been reported, at least in oral cancer cells." (PMID 30914776, 2019). "However, ANE does not activate EGFR (Tyr1068 and Tyr1173) in OECM-1 oral cancer cells." (PMID 25051199, 2014).
lymph node metastasis (178 papers, 2003 to 2026). "In terms of metastasis patterns, patients with ROS1 and RET fusions had a significantly higher incidence of distant lymph node metastases than patients with EGFR mutations (ROS1+ vs. EGFR+, 11.6% vs. 2.9%, p = 0.036; RET+ vs. EGFR+, 18.2% vs. 2.9%, p = 0.048)." (PMID 40751559, 2025). "In contrast, other mucins such as MUC1 and MUC21 have been reported in LUAD and NSCLC, with roles in immune modulation and EGFR mutation-specific expression patterns, but their associations with lymph node metastasis remain less clearly defined." (PMID 41409294, 2025). "In ECC, EGFR expression was significantly associated with lymph node metastasis, lymphatic vessels invasion, and perineural invasion." (PMID 41425711, 2025). "EGFR was found to be overexpressed and amplified in ESCC61,62, and EGFR overexpression was associated with lymph node metastasis, disease-free survival, and overall survival." (PMID 38649770, 2024). "NSCLC patients with EGFR 19-Del also had a higher risk of lymph node metastasis than those with EGFR exon 21 p.L858R." (PMID 36829178, 2023). "Tumor family history, treatment level, lymph node metastasis, EGFR mutation type, and EGFR mutation immune score combined several EGFR groups, but both groups were mostly female, nonsmoking, ≥60 years old, and leukemia patients." (PMID 37791062, 2023). "In the multivariate analysis, adenocarcinoma (HR 0.356, 95% CI 0.188–0.674), clinically undetected lymph node metastasis (HR 0.427, 95% CI 0.263–0.692), and EGFR mutation (HR 0.263, 95% CI 0.139–0.500) were favorable independent prognostic factors." (PMID 37355521, 2023). "ATG5 expression was positively associated with large tumor size, lymph node metastasis, and EGFR expression." (PMID 37735252, 2023). "With the development of radiomics in the field of molecular precision medicine, epidermal growth factor receptor (EGFR) gene mutation status and lymph node metastasis in NSCLC patients can also be well predicted." (PMID 36682020, 2023). "The sole explanation for the favorable OS observed in EGFR+/CD3+ patients was the significant association with decreased lymph node metastasis." (PMID 35957892, 2022). "In multivariate analysis, lymph node metastasis, EGFR-mutations, and ALK were independent predictors of NSCLC." (PMID 35644823, 2022). "Takuwa and colleagues reported that a patinet with SMPLA involving multiple lobes of the same lung had mediastinal lymph node metastasis, and EGFR mutation of tumors are completely different." (PMID 34544453, 2021). "Pathologically, EGFR mutation was associated with a high frequency of the lepidic predominant subtypes (p < 0.001) and a low frequency of lymph node metastasis proven by surgery (p = 0.006)." (PMID 33707479, 2021). "As for the different EGFR mutation subtypes, patients with 19-Del (13.6%) suffered from a higher risk of lymph node metastasis than with wild-type (9.1%) and L858R (5.6%), although with no statistical difference (p = 0.119)." (PMID 35049681, 2021). "In a study involving 827 ADC patients, EGFR mutation was related to a low frequency of lymph node metastasis (p = 0.006)." (PMID 35049681, 2021). "Twenty-two patients had EGFR mutations, and only one patients received adjuvant therapy due to N2 lymph node metastasis." (PMID 34544453, 2021). "Univariate analysis showed that age, lymph node metastasis, pathological grading, tumor size, epidermal growth factor receptor (EGFR) mutations, and circDCUN1D4 expression level were significantly correlated with OS." (PMID 33425493, 2021). "EGFR expression was associated with lymph node metastases (p = 0.001), liver metastases at diagnosis (p < 0.001), and advanced stage (p < 0.001)." (PMID 32170146, 2020). "On the other hand, we found that EGFR mutation was less associated with lymph node metastasis, supporting a lower stage in EGFR mutation cases." (PMID 32690092, 2020).